PDCD6IPP2 (PDCD6IP pseudogene 2)
Gene: Transcribed unprocessed pseudogene on chromosome 15 (28,801,366 to 28,818,999, forward strand). Ensembl gene ENSG00000261377.
Diseases named in the same sentence as PDCD6IPP2 in open-access papers:
PDCD6IPP2 is named in the same sentence as 2 diseases in open-access papers, as found by Europe PMC text mining. Sharing a sentence is not in itself a finding about the gene and the disease.
PDCD6IPP2 shares sentences with these, for which no sentence is quoted: lung carcinoma (1 paper); tumor (1).